PNLIP (pancreatic lipase)
Diseases named in the same sentence as PNLIP in open-access papers (continued):
Sharing a sentence is not in itself a finding about the gene and the disease.
pancreatitis (continued). "Pancreatic lipase immunoreactivity was normal and unsupportive of a diagnosis of pancreatitis." (PMID 37632111, 2023). "Although ER stress in pancreatic acinar cells predispose to chronic pancreatitis, the mixed clinical phenotype of PNLIP variants, together with moderate lipase expression, suggested that these heterozygous mutations are unlikely to induce pancreatitis alone." (PMID 35704637, 2022). "Our study showed that dogs with increased pancreatic lipase immunoreactivity concentrations could display a wide range of clinical signs, which may be related to pancreatitis or a concurrent disease." (PMID 35739917, 2022). "Measurement of canine serum pancreatic lipase immunoreactivity (cPLI) concentration by Spec cPL has been reported to have sensitivity of 42% to 90.9%2, 3 and specificity of 74.1% to 100%4 for diagnosing pancreatitis." (PMID 34250650, 2021). "The diagnosis of pancreatitis was based on abdominal ultrasound (enlarged, irregular, hypoechoic pancreas surrounded by hyperechoic mesentery and mild-to-moderate ascites) and positivity to a canine pancreatic lipase immunoreactivity test." (PMID 33195532, 2020). "It is assumed that at the onset of pancreatitis, a large amount of pancreatic lipase releases into the systemic circulation hydrolyzing serum TGs and adipose tissue, which would consequently generate high concentrations of free fatty acids with detergent properties." (PMID 29914404, 2018). "Her episodes of recurrent pancreatitis were similar to the etiologies of case 2 with acute periumbilical abdominal pain, vomiting, nausea, as well as a transient increase in the enzymatic levels of amylase and pancreatic lipase." (PMID 28196530, 2017). "The objective was to evaluate whether treatment with meglumine antimoniate could induce pancreatitis in dogs with leishmaniosis, on the basis of clinical signs, canine serum specific quantitative pancreatic lipase immunoreactivity (cPLI) concentration, and ultrasonographic abnormalities." (PMID 39716313, 2024). "Triglycerides are broken down by pancreatic lipase into glycerol and unsaturated fatty acids, and high concentrations of unsaturated fatty acids mediate calcium overload, microcirculatory disorders, inflammation, and other mechanisms to exacerbate the degree of pancreatitis injury." (PMID 38773098, 2024). "Interestingly, these studies involved referral populations or fatal cases of pancreatitis, and the prevalence of abdominal pain has been reported to be as low as 15% in a study utilizing multiple practice types and a clinical diagnosis utilizing a point-of-care pancreatic lipase assay." (PMID 35739917, 2022). "Objection has been raised that DGGR‐based lipase assays are not specific for pancreatic lipase and subject to interference from nonpancreatic lipases in healthy dogs without pancreatitis." (PMID 40747549, 2025). "Apart from occult pancreatitis, other reasons might explain the increase in DGGR lipase activity, including increased pancreatic lipase synthesis, increased cellular permeability to this enzyme, or a decreased rate of its renal clearance." (PMID 33146921, 2020). "Cases of triaditis were not included, however feline specific pancreatic lipase was not available in all cases and pancreatitis was ruled out by ultrasound." (PMID 29764431, 2018). "R122H mice showed elevated pancreatic lipase, but there was no spontaneous development of pancreatitis within 18 months." (PMID 17069643, 2006). "The dogs were not tested to rule out pancreatitis (pancreatic lipase immunoreactivity), exocrine pancreatic insufficiency (canine trypsin-like immunoreactivity), or hypoadrenocorticism (resting cortisol or adrenocorticotropic hormone stimulation test), all of which can cause gastrointestinal signs." (PMID 40979161, 2025).
pancreatitis (continued). "The incidence of postoperative pancreatitis varies among previous reports due to lack of a uniform definition: in our study, all patients with pathologic pancreatic lipase levels (> 300 units/liter) and positive laboratory signs of inflammation were classified as having this particular complication." (PMID 31166962, 2019).
diabetes (31 papers, 2013 to 2025). "We aimed at exploring the antidiabetic properties of B. gymnorhiza via inhibition of key enzymes linked to diabetes and related complications, namely, α-amylase, α-glucosidase and pancreatic lipase." (PMID 35335362, 2022). "The hyperlipidemia associated with diabetes mellitus is reduced by limited absorption of free fatty acids and free cholesterol following inhibition of pancreatic lipase and pancreatic cholesterol esterase." (PMID 30532775, 2018). "The reduced absorption of free fatty acids and free cholesterol by inhibition of pancreatic lipase and pancreatic cholesterol esterase reduces hyperlipidemia associated with diabetes mellitus." (PMID 27846886, 2016). "Reducing absorption of free fatty acids and free cholesterol by inhibiting pancreatic lipase and pancreatic cholesterol esterase reduces hyperlipidemia associated with diabetes mellitus." (PMID 24890563, 2014). "Additionally, individuals, particularly older adults, who are confirmed to be homozygous for the PNLIP p.S290N variant should be closely monitored for potential signs of chronic pancreatitis and diabetes." (PMID 40840699, 2025). "Consequently, this effect of the SP-rich extracts on pancreatic lipase activity suggests that G. gracilis may exhibit strong anti-obesogenic potentials and could be explored as an alternative therapy to limit diabetes-linked hyperlipidaemia." (PMID 39170471, 2024). "For example, Geigeria alata that is used to treat diabetes has been proven to significantly reduced the serum glucose level in diabetic rats and to possess α-glucosidase inhibitory and pancreatic lipase inhibitory activities." (PMID 38172804, 2024). "These bioactive components appear to be capable of inhibiting three essential metabolic enzymes associated with diabetes: porcine pancreatic α-amylase (PPA), dipeptidyl peptidase-IV (DPP-IV), and pancreatic lipase (PPL)." (PMID 38274210, 2023). "Since it has been documented that medicinal plants of Myanmar have properties against diabetes, some species of this region were selected to investigate their effect on porcine pancreatic lipase inhibition and glucose uptake in 3T3-L1 adipocyte assays." (PMID 37653931, 2023). "Considering complications related to diabetes, other clinical enzymes, namely, acetylcholinesterase (AChE), butyrylcholinesterase (BChE), tyrosinase, elastase and pancreatic lipase, were used." (PMID 35335362, 2022). "The hydrolyzing enzymes such as α-glucosidase and pancreatic lipase are important in diabetes control." (PMID 34073543, 2021). "Another enzyme of utmost importance in diabetes is pancreatic lipase (PL), which digests lipids, mainly dietary triacyl-glycerides, which are broken down into monoglycerides and free fatty acids that can be readily absorbed into the blood circulatory system." (PMID 34820413, 2021). "Tests for pancreatic lipase should also be performed in cases of clinical presentation of fulminant diabetes." (PMID 30400055, 2019). "In addition, QG also has α-glucosidase, α-amylase and pancreatic lipase inhibitory activities, which can be used as a potential therapeutic agent for diabetes and hyperlipidemia." (PMID 40524220, 2025). "Therefore, reducing dietary carbohydrate and lipid absorption through inhibiting α-amylase, α-glucosidase, and pancreatic lipase activities would be an effective strategy for managing diabetes symptoms." (PMID 39202492, 2024). "Importantly, exocrine pancreatic lipase and amylase frequently increase in the plasma before overt diabetes occurs, suggesting that there is a therapeutic window for the suppression of autoimmune attacks on islets." (PMID 35511238, 2022). "Moreover, the hydroalcoholic extract of L. octovalvis leaves was the most effective in the inhibition of α–glucosidases and pancreatic lipase in a screening of 23 extracts of medicinal plants reported as traditional treatments for type 2 diabetes mellitus." (PMID 30105075, 2018).
diabetes (continued). "Targeting pancreatic lipase and α-amylase by digestion-derived fractions of ethanolic-aqueous (60%, v/v) extract from Cornus mas fruit (CM) in relation to the control and prevention of metabolic disorders, including diabetes, was the first purpose of the present study." (PMID 35684087, 2022). "Therefore, it is necessary to continue the search for new alternatives to α–glucosidase and pancreatic lipase inhibitors, with milder side effects and which contribute to the treatment of obesity and type 2 diabetes mellitus, in conjunction with current therapies." (PMID 30105075, 2018). "However, acute pancreatitis without diabetes mellitus that results in ketoacidosis is an extremely uncommon manifestation brought on by elevated pancreatic lipase levels in the bloodstream." (PMID 39664920, 2024). "The production of natural inhibitors of α-glucosidase and pancreatic lipase from plant-based sources may provide an alternative means to treat diabetes or manage it without involving synthetic inhibitors." (PMID 34073543, 2021).
hyperlipidemia (31 papers, 2005 to 2025). "Previous literature suggests that diminution of free cholesterol and free acids via pancreatic cholesterol esterase and pancreatic lipase downregulate the hyperlipidemia linked with the DM." (PMID 35542112, 2018). "The effectiveness against hyperlipidemia was determined by targeting cholesterol esterase and pancreatic lipase activities, with concentrations of the compounds 5 to 12 ranging from 0.0245 to 0.268 μM." (PMID 40298778, 2025). "Pancreatic lipase serves as a primary trigger for hyperlipidemia and is also a crucial target in the inhibition of hypercholesterolemia." (PMID 39859469, 2025). "In hyperlipidemia, plasma TG levels are significantly elevated, and under the action of pancreatic lipase, they are hydrolyzed into large amounts of FFA." (PMID 39512473, 2024). "ABE reduced the food efficiency ratio in HFD-induced obese mice, consistent with its inhibitory effect on pancreatic lipase activity in vitro and postprandial hyperlipidemia an OLTT model." (PMID 37836509, 2023). "-Suppresses hypercholesterolemia and hyperlipidemia by inhibiting intestinal absorption of dietary fats mediated by pancreatic lipase inhibition." (PMID 37408757, 2023). "ABE exhibited inhibitory effects on pancreatic lipase activity in vitro and postprandial hyperlipidemia in vivo." (PMID 37836509, 2023). "The role of pancreatic lipase inhibitors in lipid metabolism is very important in reducing hyperlipidemia, especially in obese patients with metabolic syndrome." (PMID 37764670, 2023). "In this study, we found that roselle extract had an inhibiting effect on pancreatic lipase and cholesterol esterase enzyme activities, which indicates a possible mechanism of lipid lowering action to alleviate hyperlipidemia." (PMID 35487948, 2022). "In this sense, a S. herbacea extract was shown to control hyperlipidemia in diabetic mice through inhibition of pancreatic lipase." (PMID 36501107, 2022). "Hyperlipidemia, hypercholesterolemia, and elevated canine pancreatic lipase (cPL) were also noted." (PMID 40463793, 2025). "Additionally, other bioactive (e.g., glycolipid H-b2, polyphenols) are also effective inhibitors of pancreatic lipase, a mechanism surely involved on the effects of S. maxima on postprandial hyperlipidemia in young runners previously reported by our group." (PMID 31652765, 2019).
acute pancreatitis (18 papers, 2014 to 2026). An acute inflammatory process that leads to necrosis of the pancreatic parenchyma. "Chronic kidney disease (CKD) in dogs is associated with increased serum pancreatic lipase activity, complicating the diagnosis of acute pancreatitis (AP)." (PMID 42121702, 2026). "When acute pancreatitis caused TRL exposure to pancreatic lipase in pancreatic tissues, triglycerides would be hydrolyzed to release FFAs, resulting in acinar cell damage." (PMID 31570698, 2019). "The toxic effects of pancreatic lipase metabolism of excess TG release toxic free fatty acids into the circulation, which would have contributed to severe acute pancreatitis, impending cardiovascular disease (CVD), and other organ failure." (PMID 41393592, 2025). "Hypertriglyceridemic pancreatitis, a subtype of acute pancreatitis, is initiated by the enzymatic activity of pancreatic lipase on excess fat, producing fatty acids." (PMID 41048425, 2025). "Patient P3 had a documented episode of acute pancreatitis, presenting with abdominal discomfort after eating a big portion of ice cream (pancreatic lipase 289 IU/L)." (PMID 37630727, 2023). "Pancreatic lipase was elevated in two patients who were symptomatic and presented with acute pancreatitis (P1 and P3)." (PMID 37630727, 2023). "We also quantified pancreatic lipase, a marker of acute pancreatitis, in serum isolated from infected NHPs." (PMID 34241597, 2021). "Orlistat was effective at inhibiting pancreatic lipase activity in vitro, in animal experiments, triglyceride-lowering treatment significantly reduced the severity of acute pancreatitis and pancreatic necrosis." (PMID 31570698, 2019). "Severity of acute pancreatitis depends on the triglyceride level, pancreatic lipase activity, efficiency of clearing free fatty acids from serum, and severity of underlying pancreatic injury." (PMID 24995138, 2014). "For example, some authors might use a combination of clinical signs, serum pancreatic lipase concentration, and abdominal ultrasound to make the diagnosis of acute pancreatitis, while others depend heavily upon expert opinion." (PMID 32852140, 2020). "The pathophysiology of triglyceridemia-induced acute pancreatitis is not exactly known, but it is believed that pancreatic lipase is released in response to triglyceridemia, which produces high levels of free fatty acids in the pancreas." (PMID 39493173, 2024). "Lipase activity and pancreatic lipase immunoreactivity (PLI) have not been compared in dogs hospitalized for acute pancreatitis (AP)." (PMID 36468410, 2023). "Although the complete pathophysiology of hypertriglyceridemia in acute pancreatitis is not entirely clear, it is postulated that the hydrolysis of triglycerides into free fatty acids (FFA) via pancreatic lipase may induce toxic inflammatory effects." (PMID 39574983, 2024).
metabolic syndrome (17 papers, 2018 to 2025). A cluster of metabolic risk factors for CARDIOVASCULAR DISEASES and TYPE 2 DIABETES MELLITUS. "Compared to native protein, the CA-β-LG and CA-β-LGTgase complexes (ratio 1:1) exhibited significantly higher antioxidant activity and inhibitory effects on α-glucosidase, α-amylase, and pancreatic lipase, enzymes associated with metabolic syndrome." (PMID 32718063, 2020). "However, evidence is needed to assess the effect of the extract and infusion of the herbal teas on enzymes associated with metabolic syndrome, such as α-glucosidase, α-amylase, and pancreatic lipase." (PMID 39456472, 2024). "The complexes formed by the native and cross-linked proteins with CA in different molar ratios led to powders with significant antioxidant activity and were active against enzymes associated with metabolic syndrome such as α-glucosidase, α-amylase, and pancreatic lipase." (PMID 32718063, 2020). "Consumption of this functional bread, with a strong relationship with the territory, could help prevent metabolic syndrome and associated pathologies due to its antioxidant properties and inhibitory activities against key enzymes, such as α-amylase, α-glucosidase, and pancreatic lipase." (PMID 36766094, 2023). "Consuming this new functional food product, with a strong relationship with the territory, could help to prevent metabolic syndrome and associated pathologies due to its antioxidant properties and inhibitory activities against key enzymes, such as α-amylase, α-glucosidase, and pancreatic lipase." (PMID 36766094, 2023). "Tamarillo extracts exhibited strong antioxidant activity and notable inhibitory effects against key metabolic syndrome-related enzymes, including pancreatic lipase, α-amylase, α-glucosidase, and ACE." (PMID 40238593, 2025). "Methanol extracts and infusions of four different South African herbal teas were compared for composition, antioxidant capacity, and inhibition of enzymes related to metabolic syndrome (α-glucosidase, α-amylase, and pancreatic lipase)." (PMID 39456472, 2024). "Glucocorticoid inhibition of hairy enhancer of split 1 (Hes1) gene expression that regulates hepatic production of pancreatic lipase is also involved in the pathogenesis of dyslipidemia." (PMID 33633684, 2020). "Compared with the standard diet, HFFD induced dyslipidemia and liver structure alterations, and increased pancreatic lipase activity." (PMID 35541829, 2018). "Particularly, we examined AMP potential applicability in wound healing, skin infections and metabolic syndrome, considering their ability to act as potential Angiotensin-Converting Enzyme I and pancreatic lipase inhibitory peptides as well as antioxidant peptides." (PMID 34195099, 2021). "Therefore, pancreatic lipase inhibition is a goal to reduce fat absorption to control dyslipidemia." (PMID 32952589, 2020). "Metabolic syndrome-inhibitory peptides (e.g., KVEGDLK, YETGNGIK, AIGVGAIR, etc.)from a cricket protein fraction exhibited inhibitory effects on angiotensin-converting enzyme, pancreatic lipase, and α-glucosidase." (PMID 40573101, 2025). "In humans, HS (Hibiscus sabdariffa) also presented a lipid-lowering action in individuals with metabolic syndrome, showing reduction in blood glucose, total cholesterol, triglycerides and increase in HDL, through the inhibition of pancreatic lipase and reduction of intestinal lipid absorption." (PMID 39258617, 2024).
Hyperglycemia (13 papers, 2018 to 2025). An increased concentration of glucose in the blood. "It has also been suggested that flavonoids can act to reduce visceral fat accumulation and hyperglycemia by inhibiting pancreatic lipase activity and by reducing intestinal lipid absorption." (PMID 31166364, 2019). "Moreover, methoxy-7-hydroxy-9,10-dihydro-1,4-phenanthrenequinone (50 μg/m) reduced hyperglycemia via inhibiting both pancreatic lipase and α-glucosidase enzymes." (PMID 37396948, 2023). "Decorticated sorghum grain phenolics demonstrated strong inhibition of α-glucosidase, α-amylase and pancreatic lipase enzymes comparable to commonly used drugs, suggesting their possibility to decrease postprandial hyperglycemia and fat absorption by retarding carbohydrate and fat digestion." (PMID 32575757, 2020). "Therefore, the inhibition of digestive enzymes (α-glucosidase, α-amylase and pancreatic lipase) is one of the effective therapeutic strategies for controlling postprandial hyperglycemia by retarding the absorption of glucose and preventing obesity by reducing intestinal fat absorption." (PMID 32575757, 2020). "The hyperglycemia accompanied by a dyslipidemic disturbance proven by a significant elevation of TG, T-Ch, and LDL-c and a decrease in HDL-c in serum pancreatic lipase." (PMID 30034500, 2018).
hypertriglyceridemia (11 papers, 2016 to 2024). A laboratory test result indicating elevated triglyceride concentration in the blood. "A study in rats showed that tea-catechin dose-dependently inhibited pancreatic lipase activity, thereby inhibiting triglyceride absorption and postprandial hypertriglyceridemia." (PMID 38034724, 2023). "The reduction in fat absorption through pancreatic lipase inhibition is known to assist with controlling postprandial hypertriglyceridemia as an independent predictor of CVD." (PMID 34681074, 2021). "Although the mechanism of hypertriglyceridaemia -induced SAP is still unclear, the most accepted theory involves accumulation of free fatty acids in the pancreas, which results from excess TG being hydrolysed by pancreatic lipase." (PMID 30496237, 2018).